TNF (tumor necrosis factor)
Diseases named in the same sentence as TNF in open-access papers (continued):
Sharing a sentence is not in itself a finding about the gene and the disease.
asthma (continued). "Other studies using the STIM-ORAI antagonist SKF 96365 reduced key inflammatory cytokines, including IL-4, IL-5, IL-12, IL-13, IFN-γ, and TNF-α, and effectively reversed airway tissue remodeling in ovalbumin-induced asthma models." (PMID 39664985, 2024). "In two previous studies, 10 to 12 weeks of etanercept, an anti-TNF fusion protein, improved lung function, bronchial responsiveness, and asthma-related quality of life." (PMID 38710930, 2024). "The study demonstrated that TNF markers, particularly their sputum levels, are strongly correlated to clinically important phenotypes of asthma, including neutrophilic and severe asthma." (PMID 38339210, 2024). "In the context of asthma, TNF-α is known to be a significant inflammatory mediator that contributes to the pathogenesis of the disease." (PMID 39337534, 2024). "Activated eosinophils secrete a variety of cytokines during the development of asthma, including Th2 cytokines (IL-4 and IL-5), acute proinflammatory cytokines (e.g., TNF-α, IL-6, and IL-8) and chemokines." (PMID 38245791, 2024). "Human lung epithelial cells stimulated with IFN-γ, IL-1β, and TNF-α to simulate the inflammatory state present in asthma showed an up-regulation of miR-146a-5p along with an increase in 5-lipoxygenase (5-LO) activity." (PMID 38337625, 2024). "In contrast, TH1 cells release IL-2, interferon (IFN)-γ, and tumor necrosis factor (TNF)-α, possibly conferring a protective role in asthma because they can directly antagonize pathologic TH2 responses to control eosinophilic inflammation." (PMID 39439788, 2024). "The results showed that in serum, TNF-α expression in the asthma group was significantly higher than in the control group and more pronounced under PM treatment." (PMID 38273268, 2024). "In line with that, elevated TNF-α in our study group of children with asthma further suggests persistent airway inflammation." (PMID 39902293, 2024). "TNFα is a proinflammatory cytokine that has increased expression in the airways of patients with asthma." (PMID 39194521, 2024). "TNF is a pro-inflammatory cytokine that plays a role in several inflammatory diseases, including asthma." (PMID 38540714, 2024). "Asthma inflammation was characterized by elevated serum IL-6, increased lung cytokines (TNF-α, IL-6, IL-10), and higher fungal abundance confirmed by polymerase chain reaction (PCR)." (PMID 39484217, 2024). "Our investigation into the Cc10−/− asthma mouse model revealed that lung DCs exhibited substantially higher mRNA expressions of IL-6 and TNF-α compared to wild-type counterparts, 24 h after allergen exposure." (PMID 39078462, 2024). "Key cytokines such as interleukin (IL)-6, IL-8, and tumour necrosis factor-alpha (TNF-α) play critical roles in driving airway inflammation and bronchial hyperreactivity." (PMID 39458339, 2024). "Several studies have shown that phosphorylation of MAPKs triggers inflammatory and immune responses by regulating the production of TNF-α, IL-6, and other inflammatory factors in asthma." (PMID 38745671, 2024). "Consistent with the results from pre-clinical animal studies, the effectiveness of etanercept, a humanized soluble TNF receptor fusion protein that neutralizes the effects of TNF-α, has been inconsistent in the treatment of asthma." (PMID 38878250, 2024). "Noticeably, azithromycin can suppress the dysregulated TNF signaling and represents a potential approach for the treatment of asthma." (PMID 38339210, 2024). "Administration of crocin (25 mg/kg/day, PO) in mice with asthma induced by OVA resulted in a decrease in levels of TNF-α, IL-4, IL-13, LDH, and MDA, while levels of SOD and GSH in lung tissue were increased." (PMID 38419885, 2024). "Eleven genetic variants (SNPs) from the candidate genes (TNF, AGER, VEGF, and HLA-family) were selected from the literature for their previous associations with the incidence and/or severity of asthma and global MAF of at least 5%." (PMID 39766875, 2024).
asthma (continued). "Fluconazole-treated asthma mice displayed higher levels of cytokines in serum and lung tissue (TNF-α and IL-6), increased pathological scores, and a higher number of mononuclear cells in BALF, with undetectable fungal levels compared to untreated mice." (PMID 39484217, 2024). "Our experimental model of induced asthma with ALI overlap revealed a significantly increased level in TNF-α both in BALF and LTH." (PMID 38543124, 2024). "The genetic variants of TNF, LTA, VEGF, AGER, and HLA genes residing in the 6p21 region are involved in the development and progression of asthma and thus are substantial in understanding its pathogenesis." (PMID 39766875, 2024). "GA-C1 achieves the goal of treating asthma by reducing pulmonary inflammation and neutrophils, inhibiting the levels of TNF-α, IL-4, and IL-5, decreasing MUC5AC gene expression, and reducing the production of reactive oxygen species (ROS)." (PMID 39459639, 2024). "PD1 downregulated IFN-γ and TNF-α in patients with severe asthma, and PD1 alleviated infiltration and extracellular traps of neutrophils with decreased IL-6 and TNF-α in LPS-induced acute lung injury." (PMID 39720728, 2024). "TNF-α promotes the progression of severe asthma that is characterized by Th1 airway inflammation, while it also enhances Th2 inflammation in mild/moderate allergic asthma." (PMID 39337534, 2024). "The airways of individuals with severe asthma have more elastin compared to healthy controls due to the effects of TNFα, IL-1β, and TGFβ on myofibroblasts." (PMID 39194521, 2024). "In ovalbumin-sensitized mouse asthma models, exposure to wood panels of C. obtusa decreased levels of IL-4, IL-9, IL-13, and TNF-α." (PMID 38792145, 2024). "AT-RvD1 was found to downregulate TNF-α in the peripheral blood mononuclear cells (PBMCs) from both severe asthma patients and healthy individuals." (PMID 39720728, 2024). "It is known that TNF-α, IL-4, and IL-13 release is triggered by IL-33 and drives the type 2 inflammatory pattern seen in asthma." (PMID 37153601, 2023). "Other than Th2/type 2 steroid-resistant asthma, neutrophilic-steroid-resistant asthma is also prominent, with an increase in the activity of three cytokines: IL-17, IL-8, and TNF-α." (PMID 36832296, 2023). "In the present study, there was an increase in the inflammatory markers involved, such as IL-1β, IL-4, IL-5, IL-6, IL-10, IL-13, IL-17, IFN-γ, and TNF-α, in the experimental model of asthma-COPD overlap." (PMID 37511021, 2023). "AZM has immunoregulatory effects on severe asthma, reduces the levels of interleukin and TNF-α and prevents airway remodeling." (PMID 36691058, 2023). "Affected genes were enriched in asthma-relevant processes, including IL-2, TNF-α, and NF-κB signaling pathways, and were more likely to be regulated by Trichostatin A than chance." (PMID 37784136, 2023). "In the current study, ATG5 was positively correlated with TNF-α, IL-1β, IL-6, and IL-17 in adult asthma patients." (PMID 37644509, 2023). "Tumour necrosis factor (TNF)α is a pleiotropic proinflammatory cytokine involved in many aspects of asthma pathology." (PMID 36760534, 2023). "TNF‐α plays an important role in asthma and the inhibition of TNF‐α is beneficial for the treatment of chronic inflammation." (PMID 37773696, 2023). "The expression of IL-6 and TNF-α in asthmatic patients is closely related to the severity of asthma symptoms." (PMID 37492220, 2023). "In asthma, the macrophages release proinflammatory cytokines, including TNF and IL-1, which contribute to chronic airway inflammation." (PMID 38152266, 2023). "According to research, Acinetobacter baumanni activates the Nod-like receptor NLRP3 via caspase-1 to promote the release of IL-1β and TNFα from macrophages, thereby inducing asthma." (PMID 37180436, 2023). "MCP-1, IL-6, and TNF-α are key chemokines or cytokines involved in lung diseases, including asthma and COPD." (PMID 37045933, 2023).
asthma (continued). "Knockdown of RYR2 also inhibited the increase in proinflammatory cytokines, including IL-1β, IL-6, and TNF-α, in rats with asthma and spinal cord injury." (PMID 37422673, 2023). "We identified HMOX1, ITGAM, SFTPD and ADAM17 as the top novel targets for asthma which need to be validated experimentally whereas IL-18, TNF and VEGFA as the strongest therapeutic targets to investigate further for clinical benefit." (PMID 37735578, 2023). "We found that exercise intervention can effectively reduce IL-6 and TNF-α levels in children with asthma." (PMID 37492220, 2023). "Another study found that administration of ETN for 12 weeks modestly reduced AHR, improved asthma symptom control, quality of life, and lung function, and reduced the expression levels of membrane-bound TNF on peripheral blood mononuclear cells." (PMID 37377958, 2023). "TNF-α has been involved as the first cytokine appear in many lung diseases; asthma, chronic bronchitis, chronic obstructive pulmonary disease, acute lung injury (ALI), and acute respiratory distress syndrome." (PMID 36773191, 2023). "TNF-α is a cytokine with a regulatory role in inflammatory responses and the development of allergic diseases, particularly asthma." (PMID 37784136, 2023). "In our study, we observed that the salubrinal administration (DUSP2 inhibitor) reversed neutrophilic airway inflammation and cytokine responses (IL-17A, TNF-α) in a steroid-resistant asthma mouse model." (PMID 37208441, 2023). "IL-6, IL-1 and TNF-α are highly expressed in the BALF of asthma patients; these cytokines induce airway inflammatory cell infiltration and airway injury and aggravate bronchial hyperresponsiveness." (PMID 36691058, 2023). "In asthma, Th2 cytokines mediate allergic inflammation, and cytokines such as TNF-α and IL-1β amplify the inflammatory response and play a role in more severe diseases." (PMID 37511021, 2023). "SXCF treatment significantly reversed the abnormal upregulation of LMs induced by the asthma model, thereby reversing the changes of cytokines such as TNF-α and IL-4." (PMID 36937885, 2023). "Obesity is associated with exacerbation of the inflammatory and immune response in asthma patients, depending on an increased synthesis of leptin, IL-6, and TNF-α." (PMID 37108123, 2023). "Both IL-6 and TNF-α are clinically proven inflammatory cytokines found in various types of asthma induced by allergens." (PMID 37998734, 2023). "Sputum neutrophilia in asthma is strongly associated with increased production of several cytokines including IL-1β, IL-6, CXCL8, IL-12, IL-17A and TNF, and this correlates with bacterial burden, in particular Gamma-proteobacteria." (PMID 37180449, 2023). "Several pulmonary diseases, such as ALI, ARDS, asthma, COPD, and COVID-19 pneumonia, are associated with abnormal IL-6 and TNF-α expression." (PMID 37763673, 2023). "IL1ꞵ, IL-6, and TNF-α are also considered as major mediators of lung and airway inflammatory responses induced by allergen exposures in experimental and clinical cases of asthma." (PMID 37998734, 2023). "TNF-α can activate NF-κB-mediated pathways and its expression is increased in patients with severe and steroid-refractory asthma, being considered a potential therapeutic target." (PMID 37784136, 2023). "TNF-α, which is released by Th1 cells, Th17 cells, mast cells, and macrophages, is thought to be an attractive target in severe asthma." (PMID 37377958, 2023). "NF-kB regulates the expression of genes involved in both conditions, including enzymes, cytokines (such as interleukin(IL)-1, IL-6, IL-8, chemokines, and tumor necrosis factor (TNF)), which are involved in both asthma and PD." (PMID 37240888, 2023). "In the pulmonary environment, alveolar macrophages can create significant levels of TNF-α, which plays an important role in the pathogenesis of asthma." (PMID 37251328, 2023). "TNFα expression is upregulated in asthmatic lungs, particularly in patients with severe refractory asthma or neutrophilic asthma." (PMID 36760534, 2023).
asthma (continued). "IL-1RA, MCP-1, MIP-1β and TNF-α showed suppression to dexamethasone; this was only significant in the asthma group." (PMID 37404842, 2023). "Increased concentrations of TNF-α are found in people with different types of asthma after contact with allergens." (PMID 37629528, 2023). "The obese asthma phenotype is also related to the increased production of pro-inflammatory cytokines—TNF-α and IL-1β in the lung, and IL-6 in serum." (PMID 37367676, 2023). "Numerous genetic variations linked to obesity-related asthma have been pinpointed in research studies, encompassing ADIPOQ, retinoid-related orphan receptor C (RORC), IL17A, TNF-α, beta-2 adrenergic receptor (ADRB2), and IL-6." (PMID 37834850, 2023). "In obese patients, pro-inflammatory cytokines, such as IL-1β, IL-6, and TNFα, favor the pathogenesis of asthma." (PMID 36873818, 2023). "Increasing the pro-inflammatory cytokine TNF- α as a consequence of pneumonia and asthma induce ED by various mechanisms, such as increasing the endothelial permeability and reducing the endothelium- dependent relaxation." (PMID 36076196, 2022). "Thirty-one active components were probably acting through 111 biological targets, and the enriched signaling pathways for TNF, MAPK, and PI3K-Akt were associated with cough and asthma." (PMID 35807303, 2022). "A recent study suggests that pulmonary TNF-a, IL-1β and IL-6 action can affect airway functioning in asthma." (PMID 35335934, 2022). "Studies on asthma indicate that inhibiting the production of inflammatory factors, such as IL-1, IL-6, IL-8, IL-4, IL-5, TNF-α, and IFN-γ, can reduce allergic symptoms." (PMID 36307493, 2022). "Horses with severe asthma had increased TNF-α, CXCL-8, and IFN-γ concentrations in BALF supernatant." (PMID 36713876, 2022). "The heterodimer interleukin (IL)-17A/F is elevated in the lungs in chronic respiratory disease such as severe asthma, along with the pro-inflammatory cytokine tumor necrosis factor-α (TNF-α)." (PMID 36517803, 2022). "Results of specimens from patients with asthma showed that TNF-a and the TL1A/DR3 axis were overexpressed simultaneously in the airway epithelium." (PMID 35359966, 2022). "Further studies are required to investigate the efficacy of simultaneous inhibition of TNF and IL-6 on the activity of other asthma-related markers that are crucial for airway remodeling." (PMID 35408882, 2022). "TNFα levels are elevated in a variety of inflammatory lung diseases including asthma, chronic obstructive pulmonary disease, acute lung injury, acute respiratory distress syndrome, nodal disease, and interstitial lung disease pulmonary fibrosis." (PMID 36133309, 2022). "Particularly, based on literature research reports and the KEGG results, the potential mechanism of YPF in treating asthma was mainly focused on the TNF signaling pathway, PI3K-Akt signaling pathway, IL-17 signaling pathway, and Th17 cell differentiation." (PMID 36105239, 2022). "TNF-α, which is involved in the immune system in asthma, is a multifunctional cytokine secreted by the activation of macrophages and is known to promote the secretion of several inflammatory cytokines." (PMID 35837279, 2022). "This is because it is likely that following the introduction of a TNF-α-blocking drug, the Th1 response was suppressed, allowing the clinical expression of the Th2 pathway as asthma." (PMID 35163689, 2022). "Together, these novel studies show the combined effects of TNFα and IFNγ on pediatric ASM and implicate Th1-associated cytokines in promoting ASM inflammation and hypercontractility in severe asthma." (PMID 35578269, 2022). "Therapeutic approaches targeting IL-4, IL-5, and TNF-α through their selective inhibitors are under clinical trials in management of asthma." (PMID 38143476, 2022).
asthma (continued). "After immune system activation, macrophages, T cells, and other cells gather and secrete various factors, such as interleukin-1β, 4, 5, 10, and 13 and tumor necrosis factor (TNF)-a, which break the anti-inflammatory balance and aggravate asthma progression." (PMID 35359966, 2022). "TNF-α multiplied in OVA-induced asthma, which not only directly promoted the inflammation of lung tissues but also enhanced ability to migrate into lung tissues and aggravate the inflammatory symptoms of asthma." (PMID 35600943, 2022). "In an experimental asthma rat model, CBD diminished airway inflammation and IL-4, IL-5, IL-13, IL-6, IL-7 and TNF-α serum levels, which contribute to fibrosis and asthma pathophysiologies." (PMID 36556483, 2022). "TNF is a biomarker of severe asthma, and therapeutic agents that neutralize TNF were considered as anti-cytokine therapy." (PMID 35408882, 2022). "For instance, TNFα-induced CCL11, CXCL8, or IL-6 release was less susceptible to suppression by dexamethasone in ASM cells obtained from patients with severe asthma when compared to those obtained from healthy subjects." (PMID 36012240, 2022). "In the present study, TNF- α was significantly higher in children with pneumonia and asthma than pneumonia and healthy children." (PMID 36076196, 2022). "Typically, severe steroid-unresponsive asthma characterized by neutrophilia exhibits a Th2-low and Th17-high airway inflammation, with elevated levels of IL-17A, IL-17A/F and TNF-α at mucosal surfaces of the airway." (PMID 36517803, 2022). "TNFα/IFNγ was found to augment the expression of several genes that contribute to airway inflammation, hypercontractility and remodeling in asthma while also reducing expression of key anti-inflammatory genes, such as KLF15." (PMID 35578269, 2022). "KEGG enrichment analysis revealed that SYD mainly acted on asthma-related signaling pathways, with IL-4 and TNF-α being the main action targets in treating asthma." (PMID 36212941, 2022). "Several clinical studies have tested anti-TNF agents as therapeutics for patients with severe asthma." (PMID 35408882, 2022). "Studies have identified Th1 inflammation and increased TNFα levels in corticosteroid-insensitive children with obesity-related asthma." (PMID 35578269, 2022). "Building upon these studies, we performed RNA-seq to examine the individual and combined effects of TNFα and IFNγ on gene expression in the context of corticosteroid insensitivity in pediatric asthma." (PMID 35578269, 2022). "On the other hand, the TNF levels were significantly higher in patients with CPA than in those with asthma." (PMID 35628692, 2022). "Previous studies by Brown and Fitzpatrick have noted a subpopulation of children with moderate-to-severe asthma with persistently high TNFα who have poor asthma control despite high-dose corticosteroid treatment." (PMID 36385161, 2022). "Further analysis on IL-5, IL-13, and IFN-γ levels showed that compared with the normal control, the asthma group had higher IL-5, IL-13 and TNF-α levels and lower IFN-γ levels." (PMID 35210449, 2022). "Lately, investigations have determined various crucial molecules connected with asthma phenotypes, as IgE, TNF-α, and TGF-β138–40." (PMID 36344553, 2022). "Taken together, TNF-α is involved in the pathogenesis of asthma, possibly through leading to increased MMP10 expression, thereby promoting wnt/β-catenin signaling." (PMID 35000533, 2022). "TNF-α impacts asthma progression and chronic obstructive pulmonary disease is associated with IFN-γ-producing T cells." (PMID 35617421, 2022). "Analysis showed that horses with severe asthma had significantly higher TNF-α (p = 0.0005), CXCL-8 (p < 0.0001), and IFN-γ (p = 0.006) compared to healthy horses." (PMID 36713876, 2022). "TNF-α has been shown to be involved in the development of asthma, chronic bronchitis, chronic obstructive pulmonary disease, acute lung injury, and acute respiratory distress syndrome." (PMID 35371056, 2022).